TNF (tumor necrosis factor)
Diseases named in the same sentence as TNF in open-access papers (continued):
Sharing a sentence is not in itself a finding about the gene and the disease.
tumor (continued). "CD45+CD11b+/Ly6Chigh tumor‐resident monocytes were further studied by the expression of inflammatory markers TNFα and iNOS after in vitro stimulation with ionomycin and PMA." (PMID 27974353, 2017). "This process is mediated by tumor necrosis factor alpha (TNFα), which camouflages tumor cells against the immune system and is reversible upon discontinuation of therapy and resolution of inflammation." (PMID 29179523, 2017). "The inherent high level of toxicity of TNFα poses health risks, and therefore it is essential that if it is to be used for treating cancer it must be confined to the tumour site in a highly controlled manner." (PMID 28662099, 2017). "It has been shown that GMI suppressed the EGF-mediated migration and invasion via blockage of PI3K/Akt pathway and the TNF-α-induced tumor invasion and inflammation through inhibition of NF-κB/MMP-9 pathway in human alveolar epithelial A549 cells." (PMID 29050290, 2017). "Macrophage inhibitory cytokine (MIC-1) or prostate-derived factor was described as molecule that can inhibit the secretion of TNF-α by activated macrophages and reduce tumor destruction, thus influencing the microenvironment in favor of prostate cancer growth." (PMID 28487844, 2017). "Ceramides, often referred to as tumor suppressing lipids, promotes TNF‐α, produced and excreted in the white blood cells and in the endothelium, and interleukin 1B that both led to apoptosis in tumor cells." (PMID 28572944, 2017). "Among the chronic inflammation associated mediators, tumor necrosis factor alpha (TNFα), interleukin-6 (IL-6), vascular epidermal growth factor (VEGF), and MMPs are of particular attention for their role in tumor development." (PMID 28076322, 2017). "Constitutive secretion of TNF-α from tumor microenvironment is a characteristic of many malignant tumors and its aberrant expression is often associated with poor prognosis." (PMID 29238068, 2017). "In general, tumour cell lines that can produce endogenous TNFα (~5-10% of cancer cell lines) are sensitive to SMCs alone, but pro-death cytokine ligands are often required for maximal SMC efficacy." (PMID 27966453, 2017). "iTAMs are further hallmarked by the expression of CD86high, CD206low, Cd163high, Hmox1high, show a pro-inflammatory phenotype associated with the production of ROS and pro-inflammatory cytokines (TNFα and IL-6), and are capable of killing tumor cells." (PMID 29167669, 2017). "In the tumor microenvironment, neutrophils secrete a variety of cytokines including interleukin-2, interleukin-10, and tumor necrosis factor α, which further promote cancer development." (PMID 28441396, 2017). "For mice in the tumor model group and 5-FU group, the levels of glutamine, TNF-α, IL-2, and BCAAs were all lower than those of the control group, indicating that both the tumor mice and chemotherapy mice were immunocompromised." (PMID 29190948, 2017). "This study provides the first evidence that TNFR1-dependent TNF signalling constitutes a potent immune escape mechanism in a context of T-cell-inflamed tumor microenvironment, conferring resistance to anti-PD-1." (PMID 29273790, 2017). "TNF was initially described as a factor that can provoke tumour cell necrosis, but it was later recognized as a proinflammatory cytokine." (PMID 29089667, 2017). "TNF-α is mainly secreted by monocytes and is an important cytokine in apoptosis pathogenesis, anti-tumor and anti-infection." (PMID 28953987, 2017). "CM was produced through activating astrocytes either by co-culturing them in the presence of the tumor cells (CM: A 231BR) or by treatment with IFNγ and TNFα (CM: A IFNγ + TNFα), two agents known to activate astrocytes." (PMID 28008153, 2017). "Here we demonstrate the ability of apigenin to block TNFα mediated release of pro-inflammatory cytokines which are themselves responsible for inward migration of leukocytes that drive tumor growth, metastatic invasion, stem cell survival and immune evasion." (PMID 28441391, 2017).
tumor (continued). "Findings in this study suggest that several human tumor cell lines respond to docetaxel by increasing their release of TNF-α." (PMID 28915246, 2017). "Within the molecules that are increased in the tumor microenvironment, glutamate and immune factors such as TNF-α, IL-1α, and CCL2 should be taken into special consideration." (PMID 29163208, 2017). "The activated CD8+ T-cells also release high levels of inflammatory cytokines, such as interferon-γ (IFNγ) and tumor necrosis factor-α (TNFα), to induce a conducive environment for anti-tumor response." (PMID 28304339, 2017). "Increased serum TNF-α concentrations are observed in several cancers, despite tumor cells producing only small amounts of the molecule." (PMID 28030810, 2017). "Plasma inflammatory cytokines were significantly elevated in the tumor bearing group; TNF-α was over two-fold and IL-6 was over eight-fold higher in tumor-bearing mice compared to Sham animals." (PMID 29033844, 2017). "Primary human VSs obtained from patients with ipsilateral SNHL and high basal levels of tumor-secreted TNFα were selected for this study (N = 4–6 different tumors)." (PMID 29018206, 2017). "To further investigate the mechanism of upregulation of SOD-2 in AFG1-induced lung tumor, we treated A549 cells and MΦ-THP-1 cells with AFG1, TNF-α and/or IL-6 to mimic the AFG1-induced tumor-associated inflammatory microenvironment in vitro." (PMID 28801561, 2017). "As a consequence, an impaired recruitment and activity of tumor-infiltrating leukocytes resulting in decreased secretion of cytokines IL-6 and TNF-α was observed." (PMID 28881574, 2017). "Prolonged production of TNF-α in the tumor microenvironment results in increased myeloid cell recruitment in an IL-17-dependent manner." (PMID 28725636, 2017). "Our results showed a remarkable decrease in multiple proinflammatory cytokines such as TNF-a and IL-6 both in serum and tumor tissue of subcutaneous mouse model, suggesting the inhibitory effect of QRHX on cancer-related inflammation." (PMID 28630636, 2017). "Complex role of TNF-alpha in tumor pathogenesis was a subject of many studies; their authors tried to explain why this pro-inflammatory cytokine either contributes to cancer control or promotes its growth and spread." (PMID 28376925, 2017). "There, we used a Mo-DC vaccine differentiated to iDC by IL-4 and GM-CSF and to mDC by TNFα alone simultaneous to loading with autologous tumor lysate." (PMID 28601925, 2017). "T peptide promotes macrophage proliferation and increases tumor cell killing factors (TNF-α, IFN-γ) in vitro." (PMID 28228217, 2017). "NF-κB is a family of ubiquitously expressed transcription factors that are widely activated by various proinflammatory stimuli in the tumor microenvironment, including TNF-α, IL-1β and the IκB kinase (IKK) complex." (PMID 29190997, 2017). "Further, tumor-induced elevation of circulating TNFα and interleukin-6 (IL-6) was abolished in TLR4−/− mice." (PMID 28536426, 2017). "Instead, emerging evidence strongly suggests that activated immune cells within the tumor microenvironment promote EMT in IBC cells by secreting proinflammatory cytokines including TNF, IL6, and TGF-β." (PMID 28607534, 2017). "The in vivo relevance of these findings also demonstrated that deficiency in EP2 suppresses expressions of pro-inflammatory molecules, such as IL-6 and TNF-α, and factors supporting tumor cell growth, such as osteopontin, in lesions." (PMID 29259703, 2017). "Balkwill reported that TNF-α, when administered at supra-physiological levels, has powerful anti-cancer actions, but has tumor-promoting effects when chronically produced in the tumor microenvironment." (PMID 28402277, 2017). "Clinical studies have also revealed that Thal analogues, which suppress TNF, are delivered to the tumour microenvironment, augmenting the overall response to TRAIL-based treatment." (PMID 29089667, 2017).
tumor (continued). "Sub-lethal doses of 50 μg purified LPS and 5×106 salmonellae were applied, both of which caused significant systemic TNF-α responses, 100% CT26 regression, and retardation of RenCa tumor growth." (PMID 28445131, 2017). "Our results reinforced the role of TNF-α in tumor invasion, and first hand demonstrated its capacity to support colonization with lower infection doses." (PMID 28445131, 2017). "Although initially described as an anti-tumor mediator, tumor necrosis factor-alpha (TNF) is generally considered as the master pro-inflammatory cytokine." (PMID 28785220, 2017). "Inflammatory and immune cells in TME can lead to an antitumor response or pro-tumor support of growth, survival, invasion, and metastasis through secretion of several cytokines, including tumor necrosis factor-alpha (TNF-α)." (PMID 28170411, 2017). "Recent studies have highlighted the mechanisms by which the cytokines secreted by inflammatory cells and regulated by the transcription factor NF-κB such as TNF-α, IL-6 and IL-17A stimulate tumor development and progression." (PMID 28881574, 2017). "This property has rendered TNF-α a reliable read-out in various preclinical tumor models as well as a potential therapeutic adjuvant." (PMID 28445131, 2017). "L19-TNF is an armed antibody that selectively targets human TNF to EDB of fibronectin on tumor blood vessels." (PMID 28574434, 2017). "We found that TNFα strongly increased invasiveness of Colo357 cells in vitro and dramatically enhanced tumor growth and metastasis in vivo." (PMID 27542263, 2017). "Analogous to viable Salmonella SL7207, tumor regression by a specific CD8+ T cell response can be induced by purified LPS or recombinant TNF-α (rTNF-α)." (PMID 28445131, 2017). "Chemotherapeutic agents can trigger a stromal reaction within the tumor leading to TNF-α production by endothelial and other stromal cells." (PMID 29245915, 2017). "The ability of Tariquidar to re-establish both docetaxel accumulation and cytotoxicity in MCF-7TXT10 and A2780DXL12 cells suggests that docetaxel’s ability to induce TNF-α release requires drug entry into tumor cells." (PMID 28915246, 2017). "Tumor necrosis factor-related apoptosis-inducing ligands (TRAIL) is a member of the tumor necrosis factor (TNF) family that can selectively trigger rapid apoptosis in various tumor cells while leaving most of the normal cells unharmed." (PMID 29137287, 2017). "Macrophages and some of their products (IL-1, TNF, IL-6, and IL-18) are also known to increase the likelihood of metastasis while creating appropriate microenvironmental niches for preserving tumor cells." (PMID 28487844, 2017). "Some signals received from tumor microenvironments, such as tumor necrosis factor α (TNFα), transforming growth factor β (TGFβ), IL-6, fibroblast growth factor (FGF) and epidermal growth factor (EGF), can trigger EMT." (PMID 28060811, 2017). "As the systemic administration of TNF-α has major side effects, alternative strategies to selectively target tumor vessels had to be developed." (PMID 28665313, 2017). "The EC50 values for most tumor cell lines were less than 1 μM and 76 out of 77 tumor cell lines elicited TNF-α responses by Vγ2Vδ2 T cells." (PMID 28729550, 2017). "In present study, however, SLNT exhibited direct anti-tumor effects against HT-29 cells by suppressing cell proliferation and inducing cell apoptosis through ROS-mediated intrinsic and TNF-α-mediated extrinsic apoptotic pathways." (PMID 27888812, 2017). "In contrast, Tariquidar potentiated docetaxel-induced TNF-α release from MCF-7TXT10 and A2780DXL12 cells, suggesting that docetaxel accumulation within tumor cells (drug entry) is required for drug-induced TNF-α release." (PMID 28915246, 2017). "To further evaluate tumor-derived TNF-α in this induction, we added neutralizing antibody against TNF-α into our TTCS and purified-Treg co-culture system." (PMID 28817117, 2017).
tumor (continued). "TAMs are essential inflammatory cells that secrete proinflammatory cytokines as TNF-α and facilitate angiogenesis and tissue remodeling, thus promoting tumor cell motility." (PMID 29379795, 2017). "In the subcutaneous tumor model, tumor-bearing mice show elevated TNF-α, IL-6 and activin A levels that up regulate ubiquitin ligases such as muscle ring finger-1 (MuRF1) and Atrogin-1 mRNA expression in gastrocnemius muscles." (PMID 29033844, 2017). "The analysis of proton production rates in IGF1 and TNFα‐treated cells revealed differences in metabolism of normal epithelial cells from tumor‐affected versus non‐affected breasts." (PMID 28369883, 2017). "The bisphosphonate esters stimulated γδ T cells to secrete TNF-α in response to a variety of tumor cells more efficiently than their corresponding acids." (PMID 28729550, 2017). "Mechanistically, our findings argue that expression of MMP9 in tumor cellsis regulated by crosstalk of TGF-β with TNF and/or IL-1β cytokines." (PMID 28423685, 2017). "l-CDL treatment at the dose of 10 mg/kg or 20 mg/kg group significantly decreased the expression of TNF-α mRNA in spinal cord compared with the tumor group (p < 0.01), which showed stronger ability than O&A and l-THP." (PMID 28587280, 2017). "In multiple animal models, TNFα treatment has been shown to dramatically enhance tumor growth and metastasis." (PMID 28900035, 2017). "Next, a combination of purified TGF-β and TNF-α was used to replace immunosupressive tumour supernatants with similar consequences on CAL-1 cells activation by CpG, thus confirming that TGF-β prevents the down-modulation of BAD-LAMP in activated pDCs." (PMID 29030552, 2017). "RT-PCR analysis of tumour samples showed a decreased expression of TNF-α and IFN-γ, as well as the M2 macrophage marker Fizz-1 in the BPA-exposed group." (PMID 28874690, 2017). "On the other hand, NK cells activate the adaptive immune system by secreting different cytokines, like interferon-γ (IFN-γ) and tumor necrosis factor α (TNF-α), in order to regulate tumor progression and metastases." (PMID 28357137, 2017). "Neoplastic cells and tumor-associated macrophages (TAM) secrete IL-6, CSF-1, IL-10, TGF-β, TNF-α, IL-1α, angiogenic and lymphangiogenic growth factors that promote tumor development." (PMID 28830415, 2017). "PDTC blockaded C2C12 myotubes atrophy and 3T3-L1 mature adipose lipolysis induced by C26 tumor media or TNFα, suggesting that PDTC have direct effect on signaling pathways that mediated the wasting of skeletal muscle and adipose tissue." (PMID 29311924, 2017). "TNF-α also plays a significant role in tumor growth by activating macrophages through SDF-1 induction to attack T-cells and other immunogenic factors." (PMID 28346397, 2017). "Given that we observed a reduction in the levels of proinflammatory cytokines IL-6, IL-1β and TNFα within the tumour, we investigated changes in immune cell populations within the tumour and its microenvironment." (PMID 28416734, 2017). "TNFα is a factor derived from a host to induce necrosis of the tumor, which is produced in response to endotoxins." (PMID 28346545, 2017). "In line with this, it has been observed that NLGP causes activation of natural killer (NK) cells and NK-T cells and stimulates the secretion of interferon gamma (IFNγ) and Tumor necrosis factor alpha (TNFα) leading to tumor cell cytotoxicity." (PMID 28533783, 2017). "The recruited monocytes/macrophages can further release pro-inflammatory cytokines like TNF-α to accelerate tumor progression." (PMID 28107185, 2017). "Th1 Lymphocytes produce Interferon Gamma (IFN-γ), Tumor Necrosis Factor Alpha (TNF-α), and Interleukin-2 (IL-2), which are all essential for tumor rejection." (PMID 28473858, 2017). "The lack of vagal suppression of TAMs led to an increased level of TNFα promotin tumor cell proliferation and migration." (PMID 28160574, 2017).
tumor (continued). "In a microfluidically-supported human tumour biochip model, circulating ChA-treated M1 markedly reduced tumour cell viability through enhanced release of TNFα." (PMID 28134280, 2017). "Additional tumor-mediated mechanisms are responsible for stimulating osteoclasts in human MM, including IL-1, IL-6, tumor necrosis factor-α (TNF-α), TNF-β (lymphotoxin), RANKL, MIP-1α and PTHrP, among others." (PMID 29056680, 2017). "As well as other inflammatory mediators brought by the influx of inflammatory cells in the cancer stroma, TNF-α is a vital participant in tumor progression through enhancing cancer cell proliferation, survival, and migration." (PMID 29238068, 2017). "For example, TNF-α has been demonstrated as a potent mutagen that contributes to tumor initiation via the induction of reactive oxygen species (ROS) production and promoting DNA damage." (PMID 28852270, 2017). "TNF-α is a cytokine produced by foreign antigen stimulated-macrophages, which can directly kill most of the tumor cells, as well as promoting wound healing, angiogenesis and other effects." (PMID 28524080, 2017). "As cIAPs suppress TNF-induced cell death, it is likely that increased levels of cIAPs support tumor cell survival by modulating cellular responses to TNF." (PMID 28529715, 2017). "In a mouse tumor model (RipTag-5 transgenic mice), TNF-α, IL-12p70, and INF-γ expression was found to be elevated, while VEGF and TGF-β were decreased after irradiation with 2 Gy γ-rays." (PMID 28638385, 2017). "Co-administrations of anti-PD-1 with anti-TIM-3 or anti-TNF were equally effective at reducing tumor growth as compared to anti-PD-1 alone or vehicle." (PMID 29273790, 2017). "Tumor-derived cytokines and chemokines also include those promoting growth and vascularization like tumor necrosis factor-α (TNF-α) and vascular endothelial growth factor." (PMID 28589085, 2017). "Cytokines, like TNF, IL-1β, IL-4, IL-13, and TGF-β, secreted by medullary cells, can also lead to the mutation of cancer related genes, and thus, the promotion of tumor formation." (PMID 29212288, 2017). "In tumor-fibroblast co-cultures, fibroblasts increased expression of TGF-β, TNF, and IL-1β cytokines in tumor cells." (PMID 28423685, 2017). "First, neutrophils, as a type of inflammatory cells, are involved in different steps of tumor development through the production of a variety of cytokines, such as oncostatin M, interleukin-6, hepatocyte growth factor, and tumor necrosis factor." (PMID 29029493, 2017). "Various pro-inflammatory cytokines such as tumor necrosis factor-α, interleukin-1, and interleukin-6 are upregulated concomitantly with tumor progression." (PMID 29216259, 2017). "Astragalus increases the secretion of interferon and tumor necrosis factor, and activates lymphocytes, natural killer (NK) cells and macrophages against tumor." (PMID 28953950, 2017). "We found that the expression of TNF-α was lower in the microenvironment of tumor tissue compared to control tissue." (PMID 29299026, 2017). "Neutrophils produce tumor-associated vascular endothelial growth factor, interleukin, and tumor necrosis factor, all of which can disrupt the tumor stroma to facilitate invasion and metastasis." (PMID 29152134, 2017). "IL-6 promotes tumor proliferation, IL-8 leads to neovascularization, growth, angiogenesis and metastasis, and TNFα affects necrosis, invasion and metastasis." (PMID 28832545, 2017). "According to the RT-PCR and ELISA results, the tumor group exhibited significantly higher levels of TNF-α and IL-1β in spinal cord and serum compared with sham group (p < 0.01)." (PMID 28587280, 2017). "Our study shows a lower TNF-α concentration at serum level as well as a lower expression in tumour specimens of treated groups, which further validates our results." (PMID 28479926, 2017). "As detected by a CTB-Assay and a BrdU incorporation assay proliferation and viability of tumor cells were significantly increased following incubation with TNFα." (PMID 28160574, 2017).